CRP (C-reactive protein)
Diseases named in the same sentence as CRP in open-access papers (continued):
Sharing a sentence is not in itself a finding about the gene and the disease.
ovarian carcinoma (continued). "However, CRP demonstrated superior prognostic ability for lung, colorectal, and ovarian cancers." (PMID 40188292, 2025). "Therefore, it is easy to understand the fact that the CRP/albumin ratio is considered a significant prognostic factor for advanced-stage ovarian cancer patients, with a higher value of this parameter being considered as a sign of the biological decline in ovarian cancer patients." (PMID 39061143, 2024). "Therefore, clinically, CRP/Alb may be used as a complementary factor to stratify ovarian cancer patients into different prognostic groups for tailored treatment." (PMID 28431566, 2017). "Finally, CRP/Alb may be a complementary factor for tumor stage and residual tumor mass in predicting the survival in patients with ovarian cancer." (PMID 28431566, 2017). "Therefore, in this study, we retrospectively investigated the impact of preoperative CRP/Alb on the overall survival (OS) in ovarian cancer and compared the predictive value of CRP/Alb, GPS, mGPS, NLR, PLR, prognostic index (PI) and prognostic nutritional index (PNI)." (PMID 28431566, 2017). "Research findings show that compared with the healthy control group, the levels of C-reactive protein (CRP) and interleukin-6 (IL-6) in patients with ovarian cancer are elevated." (PMID 40661780, 2025). "Signal intensities for the quantified proteins overall spanned approximately seven orders of magnitude and included several previously reported ovarian cancer marker candidates, such as HE4, MSLN, VCAM-1, CEA, CRP, PROZ, LCAT, and M-CSF." (PMID 36669591, 2023). "Mean values of the markers CA125, HE4, CEA, CRP, PCT and Il-6 were higher in the group with a diagnosis of ovarian cancer." (PMID 37373969, 2023). "Statistically significant correlations were found between diagnosis of ovarian cancer and levels of CA125, HE4, CRP, PCT and Il-6." (PMID 37373969, 2023). "As a secondary analysis, we also examined abnormal CA125, LDH, and CRP levels, NLPN score, NLR, and SII, which have been reported as predictors of treatment response in ovarian cancer." (PMID 37345206, 2023). "In comparison between early (I and II according to FIGO classification) and late (III and IV according to FIGO classification) stages of ovarian cancer, statistically significant impacts were detected for the algorithm Ca125, HE4, CRP and Il-6." (PMID 37373969, 2023). "Statistically significant associations of overall survival were observed with levels of CA125, HE4, CRP, PCT and Il-6 measured at the time of diagnosis of ovarian cancer." (PMID 37373969, 2023). "Sensitivity and specificity of Il-6 in diagnosis of ovarian cancer were 46.8% and 77.8%, respectively, while for CA125, CRP and PCT were 76.6% and 63%; 68% and 57.5%; 36% and 77%, respectively." (PMID 37373969, 2023). "Elevated levels of C-reactive protein (CRP) indicate poor prognosis in a variety of cancers, including colorectal, lung, breast, and ovarian cancers." (PMID 35385679, 2022). "No further impact of gravidity, parity, height, weight, BMI, SR, CRP, NLR, MNM, and ovarian cancer histologic types on the examined Ags was confirmed." (PMID 25880896, 2015). "This study demonstrated that the circulating RTP levels were decreased in advanced stages of ovarian cancer, and that there were significant inverse correlations between RTP levels and serum CRP and NLR levels." (PMID 24396450, 2014). "In this study, circulating levels of RTP were decreased in advanced stages of ovarian cancer, and significant inverse correlations were found between RTP levels and serum levels of CRP or NLR." (PMID 24396450, 2014). "Elevated C-reactive protein is also considered a negative prognostic factor for ovarian cancer patients." (PMID 40842572, 2025). "Biomarkers such as CA‐125 and HE4 remain central to ovarian cancer prediction, with their predictive accuracy further enhanced when combined with additional biomarkers such as CEA, CA72‐4, and inflammatory markers like CRP and NLR." (PMID 40927964, 2025).
ovarian carcinoma (continued). "In contrast, patients with ovarian cancer had a more flattened distribution, with no peak in the 0–10 mg/L range, and CRP levels spread more evenly from 0 to 40 mg/L." (PMID 39771527, 2024). "Many studies have explored the relationship between C-reactive protein (CRP) levels and survival outcomes in patients with ovarian cancer (OC); however, consistent results have not been reported." (PMID 38172843, 2024). "It revealed that Il-6 is a more predictable marker of diagnosis of ovarian cancer with age, CA125, HE4, ROMA, WBC, hemoglobin, number of platelets, C-reactive protein, procalcitonin and NLR (neutrophil-to-lymphocyte ratio) and PLR (platelet-to-lymphocyte ratio)." (PMID 37373969, 2023). "In a study in ovarian cancer, CRP was higher in CTC-positive versus -negative patients, with a median of 4.33 (IQR 1.46–7.51) versus 1.52 (IQR 0.50–4.50), respectively (p = 0.001)." (PMID 37176111, 2023). "In our study, in the comparison between early (I and II according to the FIGO classification) and late stages of ovarian cancer (III and IV according to the FIGO classification), there was a statistically significant impact of the algorithm HE4, Ca125, CRP, PCT and Il-6." (PMID 37373969, 2023). "Thus, for prognostic prediction of ovarian cancer, preoperative PLR is better than CA125, NLR, fibrinogen, CRP, and albumin levels." (PMID 35464000, 2022). "In addition, an independent cohort analysis validated that CRP and ARHGEF 11 were proteins related to ovarian cancer disease progression." (PMID 33613752, 2021). "The mean value of CRP in serum was higher in women who died from ovarian cancer (11.67 mg/L) (n = 177) compared with women who did not (7.11 mg/L) (n = 112)." (PMID 31069161, 2019). "Risk estimation models were constructed for Type I (Model I) and Type II (Model II) OC from analysis of Protein Z, Fibronectin, C-reactive protein and CA125 levels in prospectively collected samples from the United Kingdom Collaborative Trial of Ovarian Cancer Screening (UKCTOCS)." (PMID 27903971, 2017). "The search terms were set to “ovarian neoplasms” OR “ovarian cancer” OR “cancer of ovary” AND “neutrophil-to-lymphocyte ratio,” “platelet-to-lymphocyte ratio,” “monocyte-to-lymphocyte ratio,” “systemic inflammation Index,” “C-reactive protein albumin ratio,” “prognostic nutritional index”." (PMID 36759864, 2023). "Nonetheless, increased serum levels of CRP and TNF-α have been detected in women as early as 5 years prior to the time of ovarian cancer diagnosis, although there is uncertainty as to whether these markers are reflective of local site inflammation pertinent to the ovarian tumor microenvironment." (PMID 35740687, 2022). "In addition, in ovarian cancer, a meta-analysis suggests that high CRP levels superior to 10 mg/L, rather than circulating pro-inflammatory cytokines might contribute to the etiology of ovarian cancer." (PMID 33708198, 2021).
hypertriglyceridemia (88 papers, 2010 to 2026). A laboratory test result indicating elevated triglyceride concentration in the blood. "Blood levels of glucose, lactate dehydrogenase, C-reactive protein (C-RP), procalcitonin, ferritin, interleukin (IL)-6 were higher in patients with hypertriglyceridemia." (PMID 38449886, 2024). "The most common laboratory abnormalities according to HLH-2004 guidelines are cytopenia, hypertriglyceridemia, hypofibrinogenemia, elevated ferritin, elevated liver enzymes, hyperbilirubinemia, and elevated CRP." (PMID 39087157, 2024). "Positive urine leukocytes, abnormal liver function, elevated C-reactive protein, hypertriglyceridemia, and increased total bile acids are the main adverse events that occurred more than once and were potentially related to the study drug." (PMID 38027026, 2023). "Increased waist circumference, hypertriglyceridemia and increased serum C-reactive protein levels in IBD patients presenting with NAFLD were each reported in one study." (PMID 37960160, 2023). "Laboratory evaluation showed microcytic anemia, elevated acute-phase reactants (ESR and CRP), hypertriglyceridemia, and elevated hepatic and muscle enzymes." (PMID 37600812, 2023). "A potential explanation is that the distribution of CRP values was very wide (13.4 ± 13.0 vs. 17.7 ± 11.8 g/dL, hypertriglyceridemia and normotriglyceridemia, respectively)." (PMID 34371797, 2021). "Those in the moderate-to-severe hypertriglyceridaemia group had a greater median CRP concentration (50.5 mg/L) compared with the mild hypertriglyceridaemia and normotriglyceridaemia groups (23.5 mg/L and 21.0 mg/L respectively)." (PMID 32859322, 2020). "On multivariate regression, moderate-to-severe hypertriglyceridaemia (OR 5.66, 95% CI: 1.87 to 17.19, p = 0.002) and an elevated C-reactive protein concentration ≥120 mg/L (OR 1.00, 95% CI: 1.00–1.01, p = 0.040) were associated with admission to critical care." (PMID 32859322, 2020). "Individuals suffering from hypertriglyceridemia had 1.93 (95% CI: [1.33–2.81]) and 2.31 (95% CI: [1.57–3.41]) times increased odds within Q2 and Q4 hs-CRP levels, respectively." (PMID 32489776, 2020). "For instance, the most significant association with the ARIC biomarker high-sensitivity C-reactive protein (CRP) was with “Hypertriglyceridemia” and the second was with the positive control diagnosis “Elevated CRP” (p = 0.0009)." (PMID 30166544, 2018). "We observed higher weight gain, hyperinsulinemia hypertriglyceridemia and elevated circulating CRP in western diet-fed Sirt3−/− mice." (PMID 30510203, 2018). "The low HDL-C group had a significantly higher rate of hypertriglyceridemia (p = 0.032) and elevated CRP level (p = 0.012) compared with the normal HDL-C group." (PMID 24625581, 2014). "The patients with hypertriglyceridemia presented a significantly lower level of CRP than those with a normal TG level (p = 0.006)." (PMID 24625581, 2014). "Decreased median HDL-C levels were significant for the patients with hypertriglyceridemia (p<0.001), elevated CRP level (p<0.001) and for those with a tobacco history (p<0.001) and a higher tobacco index (p = 0.008)." (PMID 24625581, 2014). "The main finding of the present study was the elevation of the hs-CRP level within 2 hours and prolonged hypertriglyceridemia within 4 hours as a result of a high saturated fat meal in apparently healthy non obese participants." (PMID 23369030, 2013). "Furthermore, as expected, our secondary HLH patients demonstrated significant laboratory abnormalities, including cytopenias, markedly elevated inflammatory markers (CRP and ferritin), hypertriglyceridemia, and increased liver enzymes." (PMID 40572665, 2025). "Clinical studies have indicated that patients with hypertriglyceridemia-induced AP often experience more severe abdominal pain, higher fever, and markedly increased levels of inflammatory markers such as C-reactive protein (CRP) and interleukin-6 (IL-6)." (PMID 40937420, 2025).
hypertriglyceridemia (continued). "These mice were characterized by hyperinsulinemia, hypertriglyceridemia and elevated levels of CRP." (PMID 34393764, 2021). "Furthermore, Matia-García and coworkers recently reported that young obese subjects with hypertriglyceridemia exhibit low-grade systemic inflammation characterized by increasing levels of C-reactive protein (CRP) and IL-6, accompanied by reduced IL-10 serum concentration." (PMID 29675435, 2018). "When metabolic disorders occur, the levels of postmeal glucose, C-reactive protein (CRP), and inter-leukin-6 (IL-6) increase; hypertriglyceridemia ensues and the levels of apolipoprotein A1 and HDL cholesterol decrease." (PMID 34769939, 2021). "Compared to healthy subjects, MS patients exhibited increased BMI, waist circumferences, blood pressure, hypertriglyceridemia, decreased HDL and increased levels of inflammation markers (CRP, ESR, WBC, neutrophils, lymphocytes)." (PMID 32343751, 2020). "Laboratory workup revealed pancytopenia with leukoerythroblastosis, elevated ESR, increased serum levels of transaminases, elevated CRP and LDH, hyperferritinemia, hypertriglyceridemia, proteinuria, hepatomegaly, and positive antinuclear antibody." (PMID 30729051, 2019). "Hypertriglyceridemia promotes a state of low-grade systemic inflammation, characterized by an increase in proinflammatory cytokines, such as interleukin-6 (IL-6), tumor necrosis factor-alpha (TNF-α), and C-reactive protein (CRP)." (PMID 41149060, 2025). "Blood pressure, triglycerides, total cholesterol, HDL-cholesterol, LDL-Cholesterol, visceral adipose tissue, hypertriglyceridemia, and hs-CRP were higher in HC individuals when compared to non-HC." (PMID 33028050, 2020). "On the other hand, women with moderate-to-very-severe airflow limitation had higher BMI (p<0.0001), higher frequencies of hypertriglyceridemia (p<0.0001), low HDL cholesterolemia (p<0.01), high LDL cholesterolemia (p<0.05), DM (p<0.05), and CRP (p<0.05) than in those with mild airflow limitation." (PMID 24312268, 2013).
septic arthritis (88 papers, 2008 to 2026). "Diagnostic factors in favor of septic arthritis were found to be body temperature of more than 38.5 °C, serum CRP level of greater than 10 mg/l." (PMID 38115094, 2023). "Erythrocyte sedimentation rate and C-reactive protein are reliable diagnostic markers in septic arthritis." (PMID 35664399, 2022). "When calculating the risk extremes using the model-based estimates, a patient presenting with age ≥5 years and CRP ≤ 2 mg/dl would have the lowest risk probability of 0.15 for having septic arthritis of the knee." (PMID 34790694, 2021). "Then, we found that CRP > 130 mg/L, albumin < 3.4 g/dL and preoperative antibiotics days > 8 predisposed the coexisting infections of infectious spondylitis and septic arthritis." (PMID 34830626, 2021). "Multivariate regression analysis demonstrated that tobacco use (p=0.001) and CRP (p<0.001) remained significant risk factors/predictors for septic arthritis in the overall cohort." (PMID 32566449, 2020). "When evaluating patients with septic arthritis, diagnostic accuracy of laboratory values such measurement of CRP or WBC alone is insufficient." (PMID 31954400, 2020). "Our multivariate analysis of 358 joint aspirations found smoking status as a significant risk factor and elevated CRP (>100 mg/mL) as a significant predictor of septic arthritis." (PMID 32566449, 2020). "The purpose of this study was to evaluate the efficacy of a discharge criterion of CRP < 2.0 mg/dL at preventing reoperation and readmission and to identify other potential risk factors for treatment failure of septic arthritis in children." (PMID 31850363, 2019). "Diagnostic criteria for septic arthritis (SA) should be strictly abided by clinical and biological features such as: weight-bearing status, CRP >20 mg/L and joint aspiration bacteriological results, to minimize needless antibiotic." (PMID 28241879, 2017). "The elevated CRP in 75% of the cases supports recent literature recommending the inclusion of CRP in the diagnostic criteria for septic arthritis." (PMID 27635147, 2016). "To further examine this controversy, we designed a retrospective study to evaluate serum PCT and CRP levels in children with or without septic arthritis admitted to our hospital, aiming to compare the diagnostic efficacy of PCT and CRP for septic arthritis (SA)." (PMID 41163924, 2025). "The optimal CRP cutoff of 6.49 mg/L identified in this study is lower than the traditional 10 mg/L threshold, and its significance lies in enhancing diagnostic sensitivity for pediatric septic arthritis (SA)." (PMID 41163924, 2025). "Similarly, our results indicate the diagnostic value of serum ESR and CRP level as an independent predictor of septic arthritis." (PMID 38115094, 2023). "The highest risk probability of septic arthritis of the knee was 96% for the patients less than the age of 5 years, with CRP > 2, and %PMN ≥ 85%, and the lowest risk probability of septic arthritis was 11% when patients were ≥5 years of age, with CRP ≤ 2, and %PMN <85%." (PMID 34790694, 2021). "While the patient exhibited some features concerning for septic arthritis, including fever and elevated CRP, key findings were inconsistent with infection." (PMID 40630360, 2025). "The diagnostic performance of CRP and PCT for septic arthritis was evaluated using numerical measurements and the construction of receiver operating characteristic (ROC) curves." (PMID 41163924, 2025). "Our findings substantiate the substantial superiority of CRP for the early detection and preliminary alert of pediatric septic arthritis." (PMID 41163924, 2025). "Several observational studies have shown that C-reactive protein (CRP) is an effective biomarker for evaluating septic arthritis (SA)." (PMID 40696598, 2025). "The erythrocyte sedimentation rate, C-reactive protein concentration, and white blood cell count are usually elevated in blood samples from patients with septic arthritis." (PMID 40671158, 2025).